CD1D (CD1d molecule)
Diseases named in the same sentence as CD1D in open-access papers (continued):
Sharing a sentence is not in itself a finding about the gene and the disease.
tumor (continued). "However, the expression of CD1d on mouse tumor cells seems more frequent and our preliminary data suggest that mouse primary PC cells from TRAMP mice express CD1d (data not shown)." (PMID 20072624, 2010). "However, tumor cells can evade immunity by downregulating CD1d." (PMID 41194129, 2025). "Tumor-elevated sphingomyelin, a sphingolipid enriched in the mammalian plasma membrane, has been shown to weakly stimulate iNKT cells through a mono-acylated derivative, whereas the di-acylated form is predominantly reported to act as an inhibitor when presented on CD1d." (PMID 40746558, 2025). "However, tumor cells are known to differ in CD1d expression." (PMID 38332012, 2024). "Therefore, CD1d expression in DCs is essential for iNKT cell-mediated anti-tumor immune responses." (PMID 38332012, 2024). "The altered tumor lipid metabolic profile and accumulated lipids and fatty acids that favor evading anti-tumor immunity may impair the immune-modulatory function lipid antigens recognized by CD1d-restricted T cells." (PMID 38833109, 2024). "During CAR NKT cell treatment, tumor cells might downregulate their CD1d expression." (PMID 38665921, 2024). "Consequently, the declining CD1d expression in IMPC could help the tumor cells in eluding assaults from NKT cells." (PMID 38181281, 2024). "In addition to the direct recognition of tumor cells, iNKT cells recognize lipid-CD1d combinations expressed on antigen-presenting cells (APCs), such as dendritic cells (DC) and B cells, and initiate sequential immune reaction for the more potent elimination of pathogenic cells." (PMID 36769513, 2023). "Although both cell subsets were shown to migrate to the tumor site, it is important to note that in xenograft mouse models for neuroblastoma, the frequency of tumor-infiltrated iNKT cells was drastically higher—up to 8 times—in the presence of TAMs, which were killed via CD1d." (PMID 35163561, 2022). "Furthermore, both H. pylori and LPR have been shown to induce an over-expression of CD1d in mucosal tissue, and both CD1d and lipid antigens can stimulate CD1d-restricted T cells (i.e., natural killer T cells) to further activate innate and adaptive immune cells in the tumor microenvironment." (PMID 34071118, 2021). "However, tumor cells often downregulate CD1d, and thereby evade iNKT cell recognition." (PMID 32560408, 2020). "Additionally, iNKT cells can mediate robust and direct cytotoxicity against CD1d+ tumor targets." (PMID 32708464, 2020). "Additionally, looking at the respective staining pattern for CD1d in individual tumor cells, different characteristic features with regard to the localization of CD1d expression either in the cytoplasm or on the cell membrane could be found." (PMID 31560833, 2019). "iNKT, NK, and T cells were found to accumulate at the tumor site using these targeted approaches and, in addition, treatment was not accompanied by iNKT cell anergy as iNKT cells remained responsive to repeated injections of the CD1d fusion proteins loaded with α-GalCer." (PMID 30013569, 2018). "As iNKT cells can directly kill CD1d-expressing tumor cells, one can hypothesize that the efficacy of iNKT cell-based antitumor responses can also be improved by increasing CD1d-expression levels on tumor cells as this may facilitate their recognition by iNKT cells." (PMID 30013569, 2018). "Interestingly, a role for CD1d on tumor cells was also suggested." (PMID 29375569, 2017). "Numerous studies in both humans and mice have demonstrated their ability to directly target CD1d-expressing tumor cells, recruit and activate anti-tumor effector cells of the innate and adaptive immune systems, and control the activity of immunosuppressive cells in the tumor microenvironment." (PMID 29312339, 2017).
tumor (continued). "Age-associated reductions in less abundant T cell populations, such as γδ T cells and CD1d-restricted iNKT cells, may also impair cell-mediated tumour surveillance, and a decline in the number and function of B cells may lead to a less effective antitumour humoral response." (PMID 28751932, 2017). "Comparison of antitumor response in Jα18-deficient mice (which lack only type I NKT) with CD1d deficient mice (which lack both type I and II NKT cell) revealed that type II NKT cells were responsible for suppression of antitumor responses in several murine tumor models." (PMID 29018445, 2017). "Moreover, when tumor-bearing mice received an OVA peptide/CpG-ODN vaccination combined with systemic treatments of αGalCer/CD1d-antitumor fusion proteins, a synergistic expansion of OVA-specific CD8 T cells and NK cells was obtained, as compared to each regimen alone." (PMID 29163493, 2017). "Altogether, our study in mice demonstrates that αGC/CD1d-antitumor fusion protein greatly increases the efficacy of a therapeutic CpG-based cancer vaccine, first as an adjuvant during T cell priming and second, as a therapeutic agent to redirect immune responses to the tumor site." (PMID 25426294, 2014). "Thus, the optimized DC maturation and antigen-presentation at the tumor site upon repeated CD1d-mediated immunotherapy has the potential to prolong the anti-tumor CTL response, in addition to providing an additional adjuvant boost to the initial active antitumor vaccination." (PMID 25426294, 2014). "These cells have demonstrated activity in preclinical models of melanoma and breast cancer, including CD1d-targeted and MUC1-directed CAR-NKTs, which reduced tumour growth and enhanced survival." (PMID 41559435, 2026). "Unlike conventional CAR-T cells, CAR-iNKT cells retain their ability to recognize lipid antigens via CD1d, allowing them to simultaneously engage both CAR-targeted and CD1d-restricted tumor pathways." (PMID 41148807, 2025). "The Vδ1 TCR specifically binds to MHC-like proteins within the CD1 family, such as CD1c and CD1d, as well as Annexin A2 and stress-induced ligands such as MICA/B and UL16-binding proteins, which are often upregulated in tumor cells." (PMID 40227601, 2025). "Beyond direct tumour killing, CAR‐iNKTs contribute to host immunity by cross‐priming CD8+ T cells, depleting immunosuppressive CD1d+ TAMs and MDSCs,165, 166 activating DCs, and promoting epitope spreading." (PMID 41292193, 2025). "These cells exhibit potent, multifaceted antitumor activity against GBM, including direct tumor cell killing via CAR and NK receptors and selective targeting of CD1d+ immunosuppressive cells within the TME via their invariant T cell receptors." (PMID 40946163, 2025). "Altogether, these results demonstrate that AlloCAR70-NKT cells possess a dual capacity to target both RCC tumor cells and the immunosuppressive TME by eliminating CD1d+ TAMs and MDSCs." (PMID 40885188, 2025). "These subpopulations exhibited differential expression of surface tumor antigens, including the CAR target (i.e., CD33), the NKT TCR target (i.e., CD1d), and NKR ligands (i.e., CD112, CD155, and MICA/B)." (PMID 39893165, 2025). "Allo15CAR33-NKT cells are expected to target myeloid malignancy tumor cells through multiple surface receptors, including CAR33-mediated recognition of CD33, NKT TCR-mediated recognition of CD1d, and NKR-mediated recognition of NK ligands." (PMID 39893165, 2025). "In a scenario characterized by a low tumor burden and the presence of BCMA+CD1d− tumor cells, Allo/U15BCAR-NKT cells exhibited a tumor cell elimination efficacy on a par with that of BCAR-T cells." (PMID 38584391, 2024). "Lava-051 is a 27kD humanized bispecific single domain antibody (VHH) that directly targets CD1d, and the Vγ9Vδ2 TCR chain mediates efficient killing of CD1d-expressing tumor cells." (PMID 39253082, 2024).
tumor (continued). "Histopathological examination of liver tissues obtained from HCC/NRASG12V mice revealed abundant immune infiltration in the tumor tissue and the presence of CD19+, CD5+, and CD1d+ cells." (PMID 39611128, 2024). "Considering the direct killing function of iNKT cells mediated by CD1d5,6, we explored the effect of blocking VCAM1-CD49d signaling on clearance of CD1d- and VCAM1-expressing tumor cells." (PMID 38332012, 2024). "For Vδ2 T cells, approaches include using humanized anti-BTN3A antibodies to enhance their tumor-targeting ability or employing engineered tumor-γδ TCR bispecific antibodies (e.g., CD40, CD1D) to boost their cytotoxic efficiency." (PMID 38774876, 2024). "iNKT cells and DCs reciprocally activate each other in a CD40-CD40L and CD1d-lipid/TCR antigen dependent manner, thus initiating adaptive anti-tumour immunity." (PMID 37153585, 2023). "Collectively, we have generated a first-in-class, off-the-shelf, humanized CD1d-Vδ2 bsTCE that selectively engages both type 1 NKT and Vγ9Vδ2-T cells to trigger a potent antitumor response to CD1d-expressing tumor cells." (PMID 36868236, 2023). "Further mechanismic research revealed that CD1d-activated NKT cells can recognize TAMs specifically and kill TAMs to suppress tumor growth." (PMID 36845095, 2023). "Clear tumor growth inhibition and increased survival were observed in mice receiving the combination of PBMC and either of the CD1d-Vδ2 hu-bsTCE doses." (PMID 36868236, 2023). "iNKT cells recognize and kill tumor cells via NKG2D, CD161, NKp44, and NKp80 as well as via endogenous NKT ligands loaded on the CD1d molecule." (PMID 36830717, 2023). "Compared to normal tissues, significantly higher expression for SKAP1, LAT and lower expression for CD1D, CD79B, CETP, PTGDS was found in tumor tissues in the TCGA-BRCA cohort." (PMID 37598257, 2023). "Chemical derivatives of iGb3 have been found to stimulate NKT cells in a CD1d-dependent manner and even skew the NKT cell response towards a more anti-tumor Th1 response dominated by IFN-γ secretion." (PMID 37908366, 2023). "In pre-clinical studies, GammabodyTM molecules targeting CD40, CD1d and EGFR efficiently engage Vγ9Vδ2 T-cells to kill tumor cells expressing these antigens." (PMID 35784326, 2022). "This key process was modulated by engagement of CD1d, first apoptosis signal receptor (FAS), and CD40 molecules and, of note, iNKT cell transfer into tumor-bearing mice resulted in tumor growth inhibition and decreased M2-like TAMs." (PMID 36338516, 2022). "CD1d and CD4 antibody showed the most obvious abolishment which indicates that NKT cells played a more critical role during the anti-tumor process than the CD8+ T-cells." (PMID 34983554, 2022). "Moreover, iNKT cells can be adoptively transferred across MHC barriers without risk of alloreaction because CD1d molecules are identical in all individuals, in addition to their ability to suppress graft vs. host disease (GvHD) without impairing the anti-tumor responses." (PMID 35615083, 2022). "While preclinical mouse models for α-GalCer-dependent iNKT cell-based cancer immunotherapy led to anti-tumor responses in GBM, the anti-tumor properties were CD1d-restricted in vitro." (PMID 35163235, 2022). "Type I NKT cells can also be used as effector cells for adoptive immunotherapy if tumor cells express CD1d, as NKT cells recognize tumor cells and lyse them when tumors present α-GalCer." (PMID 34208864, 2021). "In the absence of CD1d expression on tumor cells, iNKT cells may become activated by CD1d+ APCs including dendritic cells (DCs), B cells, myeloid-derived suppressor cells (MDSCs), and tumor-associated macrophages (TAMs)." (PMID 34680322, 2021). "Tumor-derived GM3 (N-glycolyl-GM3) and GD3 have been shown to regulate iNKT cell activity, including proliferation and cytokine profile, in a CD1d-dependent manner." (PMID 34298791, 2021).
tumor (continued). "Further lasso regression analysis identified seven potential prognostic markers (IL27, CD1D, NCOA6, CTSE, FCGRT, CFHR1, and APOA2) of robustness, most of which are related to tumor development." (PMID 32518711, 2020). "The treatment with α-GalCer increase the frequency of IFN-γ-producing CD1d-tetramer+-NKT cells, effector CD8+ T cells, and Th1 cells in the tumor and spleen." (PMID 31387637, 2019). "Next, we looked at expression of several common surface markers involved in tumor-immune recognition (MHC class I, CD1d, PD-L1) as well as tumor cell migration and invasion (CD44)." (PMID 31139180, 2019). "Conversely, increasing the expression of antigen-presenting molecules like CD1d by gemcitabine and cyclophosphamide and combining chemotherapy with NKT-cell activation results in enhanced tumor control and survival." (PMID 31354710, 2019). "As ceramide is a major species of lipid that can be presented by CD1d to be recognized by NKT cells, the activation of NKT cells by ceramides released from treated tumors likely modulates the anti-tumor immune response." (PMID 31620124, 2019). "Interestingly, all three lymphocyte populations were instead decreased in the blood and spleen of CD1d-anti-HER2-treated animals as compared to the untargeted CD1d treatment, which might reflect their preferential recruitment to the tumor site upon HER2 targeting." (PMID 29163493, 2017). "To explore this possibility, we stained spleen cells from the BCL1 tumor-bearing mice with antibodies against BCL1-Id, and the cell surface markers, CD1d and CD5 that identify the B10 subset of Bregs." (PMID 27959896, 2016). "To better assess the influence of CD1d in the transplant setting, we chose a primary TCL1 tumor with high percentage of CD1d expression." (PMID 27385215, 2016). "Tumor/gal cells were lysed by NKT and NK cells in an innate fashion but NKT cells also reacted to the α-GalCer/CD1d complex on splenic DCs, which had taken up debris from lysed tumors." (PMID 25389427, 2014). "As expected from the optimal T cell response, tumor growth was best delayed in mice treated with the combination of CD1d-fusion therapy and OVA/CpG-ODN vaccine, as compared to the CD1d-fusion therapy or the OVA/CpG-ODN vaccine as single agents." (PMID 25426294, 2014). "Considering the mean quantile of expression versus other probes, surface markers CD64, CD1D, CD14, CD33, CD8A, CD16b, CD45 maintain a low level in cell lines versus microdissected tumor (all lower than the 35th quantile, p)." (PMID 25380171, 2014). "The increased production of IFNγ in the tumor and spleen of WT mice treated with RT + anti-CTLA-4 in the presence of CD1d blockade supports this interpretation." (PMID 25349699, 2014). "The other option is to establish the artificial adjuvant vector cells containing tumor mRNA and α-GalCer/CD1d, which have been shown to induce tumor-specific long-term memory CD8T cell responses and to inhibit tumor growth even 1 year after single injection." (PMID 24348476, 2013). "At an E/T ratio of 10/1, 20 % targeted killing of KATO III and 50 % killing of SKBR-3 tumor cells was still obtained with 1 μg/ml (13 nM) of HER2 and/or CEA-targeted CD1d fusion proteins, demonstrating the sensitivity of this approach." (PMID 23242316, 2013). "Our results showed that the expression of the genes CD96, CD1d, CRTAM, LFA-1 and DNAM1, involved in the interaction of NK cells with target cells such as tumour cells or DCs, increased in patients with favourable prognosis." (PMID 23758773, 2013). "Enriched iNKT cells were immediately incubated with either TM40D (CD1d-hi) or TM40D-MB (CD1d-lo) tumor target cells and assayed for tumor cytolysis." (PMID 21695190, 2011). "Thus, tumor downregulation of CD1d may be advantageous for evasion of iNKT-mediated immune surveillance in the early stages of tumor progression, when antigens presented by tumor cells such as TM40D may preferentially elicit type I over type II NKT antitumor immune responses." (PMID 21695190, 2011).
tumor (continued). "In contrast to TM40D tumor growth in these mice, growth of TM40D-MB (CD1d-lo) cells varied dramatically between mouse groups." (PMID 21695190, 2011). "Having demonstrated the functionality of CD1d expression on TRAMP-C2 cells, we next asked which cytokine profile these tumor cells stimulate in primary iNKT cells." (PMID 20593019, 2010). "Constructs with both CD28 and 4-1BB co-stimulatory domains further boosted in vivo persistence and cytotoxicity against GD2+ tumours and CD1d+ suppressive macrophages, without evidence of GVHD." (PMID 41559435, 2026). "These tumor-specific glycolipids in CRC bind to CD1d and are presented to NKT cells, which then produce cytokines like IFN-γ, enhancing cytotoxic T cell activity, and recruiting other immune cells to the tumor microenvironment." (PMID 39936958, 2025). "This platform leverages a multimodal mechanism of action: killing tumor cells via CAR and NKRs (e.g., NKG2D and DNAM-1), modulating the immunosuppressive TME via NKT TCR-mediated recognition of CD1d+ TAMs and MDSCs, and targeting CD70+ alloreactive T cells via CAR, thereby reducing allorejection." (PMID 40885188, 2025). "Since, unlike MHC-Ia, CD1d is nonpolymorphic, it is an attractive target for tumor immunotherapy using engineered iNKT cells." (PMID 41148807, 2025). "Our findings unveiled that iNKT cells recognize and kill CD1d-negative target tumors via the anti-iNKT TCR mAb bound to CD32 at the tumor site, thereby bridging iNKT cells and CD1d-negative tumors." (PMID 38319156, 2024). "The anti-iNKT TCR mAb is bound to CD32 at the tumor site, thereby bridging iNKT cells and CD1d-negative tumors." (PMID 38319156, 2024). "Four separate in vivo experiments were conducted to replicate distinct tumor burdens (comprising low and high tumor burdens) and various tumor heterogeneity scenarios, involving BCMA+CD1d− MM tumor cells, BCMA+CD1d+ MM tumor cells, and BCMA−CD1d− MM tumor cells." (PMID 38584391, 2024). "This suggests that CAR-iNKT cells may be better suited than CAR-T for tumor cell types proven to express CD1d and provide rationale for treating patients with tumors positive for both the CAR target and CD1d with CAR-iNKT cells." (PMID 39170618, 2024). "In our in vivo experimental setting, we addressed the direct interaction between iNKT cells and CD1d-negative tumor cells using immunodeficient mice which does not contain other immune cells such as NK cells." (PMID 38319156, 2024). "We found that CD1d overexpression in MC38 tumor cells showed no influence on anti-tumor efficacy of iNKT cells, and knockdown of Vcam1 efficiently elevated anti-tumor efficacy of iNKT cells in CD1d expressing MC38 tumor models." (PMID 38332012, 2024). "As (non-malignant) B cells and monocytes express CD1d, targeting type 1 NKT and Vγ9Vδ2-T cells to CD1d has a potential risk of on-target off-tumor toxicity." (PMID 36868236, 2023). "There was also no tumor growth inhibition observed in CD1d−/− mice, indicating that NKT cells are necessary for controlling tumor development." (PMID 37514190, 2023). "In the absence of PBMCs, twice-weekly i.p. treatment with CD1d-Vδ2 hu-bsTCE (2 mg kg−1) did not inhibit tumor growth, whereas admixed PBMCs (in absence of bsTCE) slightly reduced tumor growth." (PMID 36868236, 2023). "As the non-specific killing of NKT cells is dependent on the expression of CD1d by target cells, NKT is not effective against CD1d-negative tumor cells; however, combining it with CAR can compensate for this limitation." (PMID 37596653, 2023). "If sphingomyelin indeed plays a regulatory role for CD1d-mediated NKT cell activation, future studies should examine the expression of ASM in tumors with the expectation that downregulation of ASM would promote tumor immune evasion of NKT cell responses." (PMID 37908366, 2023).